LMO7 (LIM domain 7)
Diseases named in the same sentence as LMO7 in open-access papers (continued):
Sharing a sentence is not in itself a finding about the gene and the disease.
tumor (22 papers, 2011 to 2025). "In this study, we discovered the association of LIM domain only 7 (LMO7) in tumor cells with the enrichment of Tregs and immune evasion at the single-cell level." (PMID 39143228, 2025). "LMO7 deficiency significantly inhibited tumor growth and increased the accumulation of antitumor TAMs and CD8+ T cells." (PMID 41208232, 2025). "In PAAD, LMO7 deficiency inhibited tumor cell proliferation and metastasis and the progression of subcutaneous hormonal tumors." (PMID 37894409, 2023). "Using these cells as a platform, we have demonstrated that intrinsic LMO7 defect causes significant suppression of tumor growth and metastasis by inducing PC apoptosis and cell-cycle arrest at the G1/S phase." (PMID 33763427, 2021). "Notably, LMO7 deficiency enhances immune-mediated tumor confinement by regulating the phagocytic activity of TAMs." (PMID 41208232, 2025). "Using these cells with loss of LMO7 function, we have demonstrated that intrinsic LMO7 defect significantly suppresses PC cell proliferation, anchorage-free colony formation, and mobility in vitro and slows orthotopic PC tumor growth and metastasis in vivo." (PMID 33763427, 2021). "LMO7 exhibits abnormal expression across various tumor types and seems to possess tumor-type-specific properties, as indicated by available studies." (PMID 39143228, 2025). "Further stratification of ductal cells revealed distinct subtypes, with LMO7 predominantly expressed in Ductal cell 2, which is primarily derived from tumor tissues." (PMID 39143228, 2025). "LMO7 modulates the tumor immune microenvironment (TIME) and regulates dendritic cells (DCs) and CD8+ T cells intrinsically through the STING pathway." (PMID 39143228, 2025). "Future studies should explore the mechanistic links between LMO7 expression and the tumor microenvironment to uncover novel therapeutic targets." (PMID 39143228, 2025). "The most notable difference was observed in the tumor-associated TGF-β protein, which significantly increased following LMO7 overexpression." (PMID 39143228, 2025). "Circ-LMO7 exerts as a tumor suppressor in OS, and the circ-LMO7/miR-21-5P/ARHGAP24 axis is involved in OS progression." (PMID 38742566, 2024). "LMO7 was involved in tumor-intrinsic innate immunity and immune evasion, while CD44 was associated with cancer stem cells and exhibits spliced variants that contribute to cancer progression." (PMID 39704173, 2024). "DAPK3 phosphorylates the E3 ligase LMO7 at S863, resulting in LMO7-STING interaction, K63-linked polyubiquitination of STING, and tumor-intrinsic immunity." (PMID 36202787, 2022). "These in vitro and in vivo results imply that LMO7 functions as an intrinsic tumor-promoting factor in PC which provides a novel therapeutic target for PC treatment." (PMID 33763427, 2021). "Genetic knockdown or knockout of LMO7 not only significantly suppresses PC cell proliferation, colony formation, and motility in vitro but also obviously slows tumor growth and metastasis in vivo." (PMID 33763427, 2021). "Contrary to the tumour‐promoting role of miR‐96, LMO7 expression was negatively correlated with cancer malignancy." (PMID 28026121, 2017). "The function of LMO7 in regulating the anti-tumor immune response of PDAC cells and immune molecules remains largely unknown." (PMID 39143228, 2025). "To further investigate LMO7’s impact on tumor immune responses and understand immune microenvironment heterogeneity in PDAC, we conducted single-cell spatial proteomic analysis using mIHC on a tissue microarray comprising 66 PDAC and 54 adjacent tissue specimens." (PMID 39143228, 2025). "LMO7 has been reported to be involved in tumor progression by fusing with other genes." (PMID 37894409, 2023). "Next, we investigated whether intrinsic LMO7 defect in Panc02-H7 cells impacts tumor growth in vivo." (PMID 33763427, 2021). "Due to this reason, LMO7 could be another therapeutic target that directly regulates miR‐96′s tumour‐promoting function." (PMID 28026121, 2017).
tumor (continued). "Therefore, LMO7 in tumor cells plays a crucial role in regulating Treg and cytotoxic T cells." (PMID 39143228, 2025). "In addition, LMO7 has been discovered to regulate tumor metastasis." (PMID 38818308, 2024). "Notably, significant functional differences are predicted between the long or short isoforms of TCF12, OSBPL1A, TRAK1, CHEK1, ANK3, LMO7 and SCIN indicating that the observed tumor associated changes in TSS usage probably have an impact on the growth properties of the neoplastic cells." (PMID 21999571, 2011). "The results indicated that CDC73, PSMC2, SOCS3, and ETV4 were substantially upregulated in tumor group than that in control group, whereas PLK2 and LMO7 were substantially downregulated in tumor group than that in control group." (PMID 41318472, 2025). "The events that showed the most decreased PSI in the tumor were those in ANKRD36 (an uncharacterized gene with an ankyrin repeat domain), LMO7 (PDZ and the LIM domain-containing), and NKTR (facilitates natural killer cell binding to targets)." (PMID 34440489, 2021). "By intrapancreatic injection of stable cells with LMO7 knockdown or knockout into wild-type C57BL/6 mice, we demonstrated that intrinsic LMO7 suppression slowed orthotopic PC tumor growth and metastasis." (PMID 33763427, 2021). "We confirmed an aberrant increase of cassette exon skipping in tumor specimens for PACSIN2 exon 8, DIAPH1 exon 2, FGFR1OP2 exon 4, MARK3 exon 16, DST exon 93, LMO7 exon 10, and RBM5 exon 7, whereas ADD3 exon 13, MAP3K7 exon 12, and MARK2 exon 15 were preferentially included in tumor specimens." (PMID 34202984, 2021). "Interestingly, the TGF-β signaling pathway between Ductal cell 1 and Tregs was not significant in either tumor samples (regardless of LMO7 expression levels) or normal samples." (PMID 39143228, 2025).
cancer (12 papers, 2011 to 2025). A tumor composed of atypical neoplastic, often pleomorphic cells that invade other tissues. "Irregular expression of the LMO7 gene has been linked to multiple types of cancer, including breast, thyroid and lung." (PMID 36303815, 2022). "LMO7 expression was up-regulated in certain cancer tissues, such as breast, liver, stomach and lung pancreas cancer." (PMID 37762205, 2023). "While having only low or limited expression in a few tissues, LMO7 has been found to upregulate in colorectal, breast, lung, thyroid, and liver cancer and plays a critical role in cancer metastasis." (PMID 33763427, 2021). "LMO7 is a member of PDZ and the LIM domain-containing protein family, implicated in cancer-related pathological conditions and the regulation of cell adhesion." (PMID 33763427, 2021). "Except for ASXL2 and LMO7, all these genes are reported to be frequently methylated in prostate and/or other cancers." (PMID 28945760, 2017). "In addition, the current studies about the role of LMO7 on cancers generated controversial information." (PMID 33763427, 2021). "As miR‐96 targets LMO7 to promote cancer proliferation, migration and drug resistance, we continued to investigate whether overexpression of LMO7 was able to reverse the stimulating effects of miR‐96." (PMID 28026121, 2017). "Notably, some of these genes, like LMO7 and CD44, had been previously implicated in cancer." (PMID 39704173, 2024). "Collectively, these findings demonstrate the critical role of LMO7 in orchestrating TAM phagocytosis and suggest that LMO7 inhibition is a promising drug target to enhance cancer immunotherapy." (PMID 41208232, 2025). "To understand the molecular mechanism of miR‐96 in promoting cancer cell growth, we performed a search of miR‐96 sequence and found that seed‐matching sites exist between miR‐96 and 3′‐UTR of LMO7." (PMID 28026121, 2017).
LMO7 also shares sentences with these, for which no sentence is quoted: papillary thyroid carcinoma (3 papers); non-small cell lung carcinoma (2); Sensory hearing loss (2); adenoma (1); breast tumor (1); cardiomyopathy (1); ciliopathy (1); glaucoma (1); hepatocellular carcinoma (1); infection (1); lymph node metastasis (1); oropharyngeal squamous cell carcinoma (1); pancreatic neuroendocrine tumor (1); prostate tumor (1); X-linked Emery-Dreifuss muscular dystrophy (1).